ENSG00000224015 (novel transcript)
Gene: Long non-coding RNA gene on chromosome 5 (132,129,951 to 132,181,241, reverse strand). Ensembl gene ENSG00000224015.
Gene Ontology:
Molecular function: triplet codon-amino acid adaptor activity
Biological process: translation